CD68 (CD68 molecule)
Diseases named in the same sentence as CD68 in open-access papers (continued):
Sharing a sentence is not in itself a finding about the gene and the disease.
tumor (continued). "Our next objective was to investigate macrophage populations in the breast TMA by first analyzing the expression of CD14 (monocytes), CD68 (all macrophages), and CD163 (M2 macrophages), and further stratifying the expression of these markers within PDLIM2-positive and -negative tumours." (PMID 36531051, 2022). "Despite not detecting elevated ATF-3 expression or CD68+ macrophage density, MC38 tumor development led to significant mitochondrial dysfunction in the DRGs of tumor-bearing animals, by the third week after MC38 injection (n = 4 biological replicates/group in duplicates)." (PMID 35962398, 2022). "Further analyses demonstrated that of the tumours with high macrophage infiltration (CD68 moderate/high scoring stroma), 70% of these were CD68+/CD206+, compared with PDLIM2- negative stroma where 54% of macrophages expressed CD68 and CD206." (PMID 36531051, 2022). "Across tumor types, the predominant TREM-1 staining pattern observed was moderate to strong TREM-1 staining in a fraction of tumor-infiltrating myeloid cells that co-expressed CD68, with negative staining in tumor cells (pattern P-1)." (PMID 34956864, 2021). "Furthermore, by analyzing the features of the tumor immune microenvironment of patients, we found that the percentages of CD15+ and CD68+ cells in non-responders were higher than those in responders." (PMID 34025640, 2021). "On the other hand, the correlations of MIF scores with CD68, CD11c and CD163 scores in tumor nest and tumor stroma of NPC patients showed no statistical significance, suggesting that MIF may not directly affect to CD68, CD11c and CD163 in NPC." (PMID 34407796, 2021). "Furthermore, immunofluorescence double staining revealed that the primary S100A9-expressing cells in adjacent nontumoral tissue were CD15+ neutrophils, and both CD68+ macrophages and CD15+ neutrophils expressed S100A9 in HCC tumor tissues." (PMID 34157683, 2021). "While some studies have observed no prognostic role, in others both the number of CD68+ cells and soluble CD163 have correlated to poor overall survival (OS); however, only CD68+ cell counts at the invasive front of the tumour have been found to be independent predictors of reduced survival." (PMID 32843682, 2020). "The most distinctive group, named Tumor Associated Macrophages (TAM; 38% ± 13%) expressed CD16 and restricted lineage markers (CD68, CD163) and was consistently present in all tumor cases, but only occasionally in the non-neoplastic samples (Case #8 and 3 normal myometria, not shown)." (PMID 31959856, 2020). "Although PMTs have been reported to be negative for CD68, S-100, and CD34 staining, in this study, and our previous study, the tumor cells of PMTMCTs and PMTMECTs showed consistent diffuse positive staining for CD68 and variable focal positive staining for S-100 and CD34." (PMID 32049812, 2020). "Interestingly, the antibodies to HIF1A and LGMN also labeled some tumor cells, whereas anti-CD163 and anti-CD68 did not." (PMID 31434729, 2019). "In our human TMAs, we found that high expression of miR-21 in CD68+ macrophages within the TME compartment had a negative impact in patient disease-specific survival and shows the relevance of miR-21 in macrophages for tumor progression." (PMID 31710308, 2019). "However, the densities of tumour infiltrating CD3+, CD8+, FoxP3+ T cells, CD68+ macrophages and neutrophils did not significantly correlate with serum MMP-8 levels, when the correlations were adjusted for tumour stage, patient age and patient gender." (PMID 29808017, 2018). "Furthermore, PD-L1 expression co-localized with CD68 and CD163, suggesting that in this case PD-L1 is primarily expressed by myeloid cells rather than tumor cells." (PMID 28344870, 2017).
tumor (continued). "In multivariate analysis, high ph-STAT3 tumour cell expression was significantly associated with improved CSS (HR 0.69, 95% CI 0.51-0.95, P=0.030) independent of LVI, BVI, CD68+ macrophage infiltrate, CD8+ T-lymphocyte infiltrate, tumour budding and locoregional treatment." (PMID 27769057, 2016). "Interestingly, although MHC-II expression did not statistically correlate with the total immune cell infiltrate in tumor islands (p=0.097), it strongly correlated with a high presence of both CD4+ TH (p=0.047) and CD8+ CTL (p=0.012), but not with CD68+ cells (p=0.099)." (PMID 39035008, 2024). "CD68+ macrophages in the stroma and total areas were markedly higher in COPD patients than in non-COPD patients; although the difference was not significant in the tumor area, it showed a favorable statistical trend in COPD patients compared to non-COPD patients." (PMID 37388220, 2023). "The heatmaps of marker expression on the reduced dimensions showed that CD68 is the classical biomarker that is highly expressed by a large majority of macrophages; however, CD5L and MRC1 are differentially distributed with specific expression in adjacent non-malignant or tumor tissue." (PMID 36902024, 2023). "Tumor immune infiltration analysis by CIBERSORT showed a significant correlation between PZP expression and several immune cell infiltrations, and IHC further confirmed a positive correlation with CD4+ T-cell infiltration and a negative correlation with CD68+ M0 macrophage infiltration." (PMID 37509617, 2023). "The univariate and multivariate analyses revealed that individual expression of EMR1-TC, CD68, and CD163 in tumor centers could not notably predict RFS or OS, but combined EMR1-TC+CD68+CD163+ expression in the tumor center area significantly correlated with worse RFS in CRC." (PMID 36551877, 2022). "Importantly, the density of the CD68+CD206+ M2 macrophages significantly increased at the time of PD following cetuximab-based treatment (P = 0.039), whereas it did not consistently change between the tumor pairs of PR/SD (P = 0.700)." (PMID 35102212, 2022). "Interestingly, unlike CD68 and CD163, the expression of CD206 on each TAM population was not differential across the TS areas and only the CD68+CD206++ macrophages showed slightly increased expression within the tumor-nest." (PMID 31477692, 2019). "However, OS was significantly longer for patients with concurrent high PD-L1 and high CMTM6 expression as compared to the remaining cases in stroma (23m vs. 6m, p = 0.02) and CD68 (22m vs. 6m, p = 0.03), but NOT in the tumor cell compartment (22m vs. 12m, p = 0.15)." (PMID 30400835, 2018). "Total human CD11b+ myeloid cells were purified from the tumor or spleen of HSC-NOG-hIL-6 Tg mice or HSC-NOG non-Tg mice, as we could not obtain sufficient numbers of TAM-like cells when we gated HLA-DRlo/− IL-4Rα+ CD163+ CD68+ cells." (PMID 29456539, 2018). "However, the number of CD68-positive macrophages and CD163-positive macrophages in tumor stroma, and the levels of CD68 and E-cadherin expression in tumor cells did not shown any significant correlation with overall survival." (PMID 26769084, 2016). "In addition, this study also demonstrates that RT, no matter given before or after tumor implantation, alters tumor microenvironments so that not TAM aggregate in hypoxic regions, and Gr-1 positive neutrophils, CD68+ TAMs, and F4/80+ TAMs resegregate into different microenvironments." (PMID 22888475, 2012). "However, since our patient had positivity for both CD68 and CD163, which is considered to indicate poor prognosis and since the patient requested postoperative adjuvant radiotherapy, we irradiated the whole breast on the affected side, without subsequent dosing in the tumor bed area." (PMID 41256322, 2025).
tumor (continued). "Interestingly, we found that in PD-L1+ tumours (PD-L1 combined positive score (CPS) ≥1), patients belonging to CLEC7A/CD68 high subgroup held more non-responders compared with CLEC7A/CD68 low subgroup, indicating that Dectin-1+ TAMs might be involved in resistance to anti-PD-1 therapy." (PMID 37422529, 2023).
cancer (409 papers, 2010 to 2026). A tumor composed of atypical neoplastic, often pleomorphic cells that invade other tissues. "This review examines inflammatory memory in adipose tissue, focusing on CD68+ macrophages and their role in cardiometabolic and cancer risk during weight cycling." (PMID 42196186, 2026). "A high level of infiltration by CD68-ST cells was associated with worse prognosis, and a high level of infiltration by CD68-ST cells was associated with a lower risk of death from cancer." (PMID 39201801, 2024). "The positive correlations of VDR expression with the expression of FAP (cancer-associated fibroblast marker), CD68 (macrophage marker), or CD15 (neutrophil marker) were experimentally verified in PTC tissues." (PMID 38639057, 2024). "A high level of infiltration by CD68-ST cells was associated with a worse prognosis, and a high level of infiltration by CD68-ST cells was associated with a lower risk of death from cancer." (PMID 39201801, 2024). "Tumor-associated macrophages (TAMs, CD68+) are a major part of innate immunity and are elevated in many cancers." (PMID 39201801, 2024). "Using immunofluorescence, we found DAB2 to co-localize with CD68 macrophage marker in both the cancer associated stroma and within epithelial areas of HGSOC tissue." (PMID 37815603, 2023). "To further elucidate the potential immune mechanisms of CD68, we next compared the association of CD68 expression with various checkpoint markers in different cancer types." (PMID 35550532, 2022). "CD68 is also a well-established pan-macrophage marker used as a cancer-associated diagnostic and prognostic marker." (PMID 36686729, 2022). "A higher degree of CD68+ macrophage infiltration is associated with poor prognosis of different types of cancer, including NSCLC." (PMID 36520870, 2022). "High expression, however, of SIRPα by CD68+ TAMs was linked with CD47 expression by cancer cells, low TIL-score, and poor prognosis." (PMID 35406573, 2022). "In alveoli, CD68 protein was positively and strongly associated, among others, with genes involved in cancer development such as KTM5A23 or TMEM20524." (PMID 36575294, 2022). "In contrast, high SIRPα expression by CD68+ TAMs (SIRPα/CD68-ratio) was linked with CD47 expression by cancer cells, low TIL-score, and poor prognosis (p = 0.02)." (PMID 35406573, 2022). "We then performed dual in situ hybridisation with αSMA, indicative of stromal cells, specifically cancer-associated fibroblasts, and CD68, representing macrophages." (PMID 34439122, 2021). "An association of CD68+ TAMs with relative risk of cancer recurrence was also reported, while the chance of cancer-related death was almost two times higher in CD68+/iNOS− patients." (PMID 33557173, 2021). "Similar to the cancer regions, most MC&M-associated pixels in contact with T cells were CD68+ and CD163+." (PMID 30619287, 2018). "The intra-epithelial CD68+/CD45+/CK8/18−/E-cadherin− macrophages were commonly associated with cancer cells (CD68−/CD45−) that showed reduced E-cadherin levels in human DCIS samples (N = 12) as measured by quantitative image analysis." (PMID 29295986, 2018). "Loss of MUC2 and strong expression of IL-6 and CD68 were also detected in serial sections of one specimen from another patient with stage IIA cancer (lower left and lower right)." (PMID 28725043, 2017). "None of the markers of inflammatory cell infiltrate, including CD68+ were associated with cancer-specific survival." (PMID 22240784, 2012). "Although CD68 is traditionally associated with phagocytosis, recent studies linked its increased expression to poor prognosis in several cancers, including hepatocellular, lung and other cancers." (PMID 40395327, 2025). "LAMP-4/CD68 has been proposed as a cancer-associated diagnostic and prognostic marker." (PMID 40277899, 2025).
cancer (continued). "Similarly, higher macrophage counts associated with cancer tissues when compared with borderline, interestingly, CD68 and CD163 touching cell counts, were significantly associated with malignant tumours." (PMID 38674108, 2024). "Many studies have demonstrated that high infiltration of TAMs, as defined by CD68 expression, is associated with poor clinical outcomes in many cancers, including breast, lung, pancreatic, gastric, prostate, and ovarian cancers; hepatocellular carcinoma; melanoma; and glioblastoma." (PMID 39516356, 2024). "In order to validate the correlation between VDR expression and immune infiltration, the expression of VDR and cell markers including FAP (cancer-associated fibroblast marker), CD68 (macrophage marker) and CD15 (neutrophil marker) in PTC tissues was examined by qRT-PCR." (PMID 38639057, 2024). "Among the HLA genes, HLA-G gene expression was found to be upregulated when cells develop malignant phenotype, and it is identified to be associated with cancer inflammation, expressed in both cancer cells and immune cells, especially in CD68+ macrophages and CD8+ T cells infiltrating cancer tissue." (PMID 34306024, 2021). "Moreover, there was a trend that CD68+CXCL5+ macrophages in the stroma around the edges of the cancer nests to be associated with MUC1-ST expression." (PMID 33149188, 2020). "A recent meta-analysis indicates that pan-macrophages (CD68+) are favorably associated with overall survival; however, CD68 can occasionally be expressed in stromal and cancer cells themselves; therefore, the data obtained by using this marker should be carefully assessed." (PMID 32962159, 2020). "Similarly, CD3+ T-lymphocytes and CD68+ macrophages were preserved during culture, both in cancer-associated and residual pancreatic stroma." (PMID 30765891, 2019). "Furthermore, elevated expression of AGM was found in cancer-associated fibroblasts (CAFs), and this expression was correlated with macrophage infiltration as detected by CD68 antibody and with cancer invasiveness." (PMID 24737780, 2014). "Increased levels of CD68 + and CD4 + FOXP3 + cells (above the 75th percentile) were linked to worse cancer-specific survival (CSS) in patients with ccRCC." (PMID 39751643, 2025). "IDO is an intracellular enzyme that is primarily expressed in antigen presenting cells such as in dendritic cells (CD11c+) and MΦ (CD68+) and represents a mechanism of acquired immune tolerance in cancer." (PMID 40432828, 2025). "To further investigate the spatial relationship between MDH1 and the macrophage marker CD68, we used a pan-cancer spatial transcriptomics dataset." (PMID 40948768, 2025). "Conversely, in STAD, high CD68 expression correlated with better survival outcomes, indicating a potential protective role of CD68 in this cancer type." (PMID 40918116, 2025). "Some features, such as the proportion of cancer cells positive for Ki67 and the proportion of CD68 Macrophages positive for PD-L1, were consistent across compartments." (PMID 39975273, 2025). "The total amount of TAMs is often used to evaluate their correlation with cancer progression, and CD68 is a general macrophage marker for quantifying total TAM levels." (PMID 40918116, 2025). "The top three features from the primary tumors were the B cell / NK cell ratio in the cancer core, the density of CD68 macrophages, and the proportion of CD4+ T cells positive for Vimentin." (PMID 39975273, 2025). "Our study revealed strong positive correlations between CD68 expression and the infiltration levels of various TIICs, including B cells, CD4+ T cells, CD8+ T cells, macrophages, NK cells, and cancer-associated fibroblasts, across all DSC types." (PMID 40918116, 2025). "We explored the relationships between CD68 expression and six TIICs (B cells, CD4+ T cells, CD8+ T cells, macrophages, NK cells and Cancer associated fibroblast) focusing on COAD, ESCA, LIHC, PAAD and STAD." (PMID 40918116, 2025).
cancer (continued). "The expression of specific biomarkers such as CD47, CD68, and CD163 is associated with these TAMs and has been studied extensively in relation to cancer prognosis." (PMID 39682556, 2024). "The CD68 total cell count (p = 0.04), intratumoral average (p = 0.01) and touching cell average (p = 0.006) were higher in cancer." (PMID 38674108, 2024). "A study on epithelial ovarian cancer patients showed that metformin combined with platinum, in comparison with platinum alone, significantly reduced CD68+ macrophages and cancer-associated MSCs in TME of 38 cancer samples." (PMID 38659591, 2024). "In contrast, the densities of nTOB1+FOXP3+ Tregs, cTOB1+FOXP3+ Tregs, nTOB1+CD68+ macrophages, and cTOB1+CD68+ macrophages were higher in cancer tissues than in paracancerous tissues (P = 0.003, P < 0.001, P < 0.001, and P < 0.001, respectively)." (PMID 38617839, 2024). "The density of FOXP3+ Tregs and CD68+ macrophages were relatively higher in cancer tissues than in paracancerous tissues (P = 0.002 and P < 0.001, respectively)." (PMID 38617839, 2024). "Double immunofluorescence staining showed that GSDMB+ immune cells in cancer stroma were mostly CD68+ cells and S100A8+ cells." (PMID 38711020, 2024). "CD4 was increased in the surrounding stromal leukocyte regions, and CD45, CD20, and CD68 were higher in immune-rich cancer cell islet regions." (PMID 38611634, 2024). "As expected, metastatic liver tumours, identified by the presence of CK19+ cancer cells, showed a significant expansion of PDGFRβ+ mesenchymal cells and a marked increase of CD68+ macrophages compared to healthy liver." (PMID 38678021, 2024). "This revealed that the number of Meflin+ CAFs significantly correlated with that of CD68+ TAMs in both cancer types." (PMID 38849479, 2024). "Investigating the amount and spatial localization of key immune cell participants such as CD8+ and CD68+ cells will contribute to a better understanding of antitumor IR and its prognostic value in this type of cancer." (PMID 37109686, 2023). "CD68+ macrophages have been related to both favorable and unfavorable outcomes in different types of cancer." (PMID 36864443, 2023). "Some markers CD14 (monocyte), CD3D (CD4+T cells), CD3E (CD8+T cells), CD68 (macrophage), CST3 (myeloid cells), GNLY (NK cells), KRT18 (epithelial cells), and NKG7 (NK cells) were positively associated with TMSB10 in all cancers." (PMID 37275863, 2023). "The expression levels of IGSF6, CD8+ T cells, CD4+ T cells and CD68+ macrophage cells in cancer tissues from CRC patients and CRC cell lines were evaluated." (PMID 37989761, 2023). "The corresponding spatial map of local metabolite competition was visualized for cancer and CD68+ cells." (PMID 38086839, 2023). "CD4+ T-cells and CD68+ macrophages predominate in the stroma around the invasive cancer margin in these lesions." (PMID 36980751, 2023). "Using multiple immunofluorescence staining, we found that the expression level of XCL2 was upregulated in many cells in pan-cancer samples, and the number of M1 macrophage marker CD68 and INOS-positive cells increased." (PMID 37905956, 2023). "The classification of GCTs into benign, atypical, and malignant tumours is based on histological criteria and immunohistochemistry for S‐100 and CD68." (PMID 37275416, 2023). "CD68 plays a critical role in promoting cancer cell phagocytosis, is upregulated in various types of cancer, and is a hallmark of poor antitumor immunity and adverse prognosis." (PMID 37790755, 2023). "Higher expression of proteins associated with T cells, B cells, NK cells, and macrophages (such as GZMB, FOXP3, PD-1, CD20, CD56, and CD68) were observed in the ‘immune-rich cancer cell islets’ cf. ‘surrounding stromal leukocyte’ regions." (PMID 37046826, 2023). "In our preclinical studies of both GBM and peripheral cancers, we have noticed a profound role of TAMs in initiating a cascade of events involving activated NKp46+ NK cells and CD68+ Tc cells." (PMID 36902456, 2023).